NTRK1 (neurotrophic receptor tyrosine kinase 1)
Diseases named in the same sentence as NTRK1 in open-access papers (continued):
Sharing a sentence is not in itself a finding about the gene and the disease.
tumor (continued). "The rearrangement of NTRK1 constitutively activates the receptor and its downstream signaling, which mediates tumor growth." (PMID 36499051, 2022). "The expression level of NTRK1 in the primary tumor and the normal cells is significantly different (p-value =1.73×10−3)." (PMID 35627227, 2022). "As we understood, the oncogenic and tumor-suppressive nature of NTRK1 depends on several things, such as the tumor environment and NTRK1 splicing patterns." (PMID 35627227, 2022). "Gene fusions involving NTRK1, NTRK2 or NTRK3—which encode the TrkA, TrkB and TrkC receptor kinases, respectively—are found throughout a wide range of human neoplasms." (PMID 33921435, 2021). "While some of them are specific to specific tumor types, others, like NTRK1–3 fusions, are found in various solid tumors." (PMID 33963267, 2021). "The finding that FGFR1 is hardly expressed and NTRK1 mRNA expression is high provides clear evidence for the anti-tumor effect of AZD4547 in KM12(Luc) (TPM3-NTRK1)." (PMID 34790577, 2021). "HDC, GATA2, SLC45A3, and NTRK1 were downregulated in tumor-bearing mice subjected to chronic unpredictable mild stress (CUMS)." (PMID 34650925, 2021). "As well as entrectinib, gilteritinib inhibited the tumor growth and NTRK1 autophosphorylation compared with vehicle control." (PMID 33627640, 2021). "Others such as ROS1 rearrangement, RET fusion, HER2 mutation, NTRK1 fusion, and BRAF V600E mutation were detected in 7.9% of CSF and 11.1% of tumor tissues but only 4% in plasma." (PMID 34671549, 2021). "Our study suggests the potential of CHRNB4 as a target for direct regulation of HNSC tumor cells and the potential of NTRK1 as a target for regulation of mast cells." (PMID 34912722, 2021). "One of the FISH positive cases had a positive NTRK1 separation signal in 22% of the tumor cells, while its IHC result showed a strong cytoplasmic stain in 80% of the tumor cells." (PMID 34490345, 2021). "Mutations involving effectors of the mitogen-activated protein kinase (MAPK) pathway such as RET, BRAF, RAS, and NTRK1 occur in approximately 70% of patients with PTC and are associated with histopathological and biological tumor behavior." (PMID 34325712, 2021). "NTRK fusions: NTRK1, NTRK2, and NTRK3 are actionable drivers of tumor growth, and these genes encode the tropomyosin receptor kinase (TRK) family of receptor tyrosine kinases, proteins TRKA, TRKB, and TRKC, respectively." (PMID 33673070, 2021). "NTRK1 fusions are a tumor-agnostic marker with an FDA-approved indication for treatment with larotrectinib." (PMID 34385467, 2021). "Overall, entrectinib achieved anti-tumor activity against tumors harboring NTRK1, NTRK2, and NTRK3 fusions, including CNS activity." (PMID 34209967, 2021). "The tumor was confirmed by NGS to harbor a novel PEAR1-NTRK1 fusion with the 5′ end of NTRK1, including the kinase domain, starting at exon 9 fused to exon 15 of PEAR1." (PMID 32411236, 2020). "The overexpression of Ntrk1 significantly enhanced tumor size in vivo, corroborating the in vitro growth data." (PMID 30986992, 2019). "Our data indicate that Ntrk1 regulates KP cell biology including cell growth and invasion in vitro while also impacting the tumor-infiltrating immune populations and their functionality with a consistent promotion of an exhausted microenvironment." (PMID 30986992, 2019). "Ntrk1 overexpressing cells also demonstrate a robust increase of PD-L1 expression at 5:1 and 20:1 ratios of splenocytes to tumor cells at the protein level." (PMID 30986992, 2019).
tumor (continued). "The prevalence of NTRK1–3 gene fusions in this group ranged from 0.13% to 17.7% depending on the various tumour types." (PMID 31738427, 2019). "Lastly, we found that Ntrk1 regulates Jak/Stat signaling to promote expression of PD-L1 on tumor cells." (PMID 30986992, 2019). "Our data indicate that Ntrk1 regulates KP tumor cell invasion, migration, as well as signaling downstream to survival and growth pathways." (PMID 30986992, 2019). "We identified Ntrk1 as a top lead hit as being essential for tumor cell survival in vivo when challenged with an anti-PD-1 antibody and therefore a potential avenue of acquired resistance." (PMID 30986992, 2019). "The depletion of Ntrk1 alone was sufficient to reduce tumor burden, with the addition of anti-PD-1 treatment further repressing tumor growth." (PMID 30986992, 2019). "In the same trial with larotrectinib, one patient with a tumour harbouring an NTRK1 gene amplification had a single 11 mm target lesion shrink by 5 mm (45.5%)." (PMID 31738427, 2019). "Sequencing for the barcoded shRNAs revealed Ntrk1 was significantly depleted from mesenchymal tumors challenged with PD-1 blockade, suggesting it provides a survival advantage to tumor cells when under immune system pressure." (PMID 30986992, 2019). "Together, these data suggest that Ntrk1 activates Jak/Stat signaling to regulate expression of immunosuppressive molecules including PD-L1, promoting exhaustion within the tumor microenvironment." (PMID 30986992, 2019). "The FDAome in vivo dropout screen revealed Ntrk1 as a novel regulatory molecule of both KP tumor cell intrinsic biology and extrinsic immune microenvironment factors." (PMID 30986992, 2019). "Due to the presence of multiple driver gene alterations, and the unavailability of NTRK1 inhibitor, the patient then received mediastinal tumor palliative radiotherapy (DT = 18Gy/9F), but responded poorly to the treatment and deceased 16 weeks post-operation." (PMID 31208361, 2019). "Because Ntrk1 was originally identified from the FDAome hairpin screen as being necessary for tumor cell survival when under immune-mediated pressure via PD-1 blockade, we wanted to determine if Ntrk1 modulates the immune compartment within tumors." (PMID 30986992, 2019). "Expression analysis further revealed the dramatic upregulation of RET and NTRK1 fusion transcripts in the tumours relative to their matched normal tissue." (PMID 31653970, 2019). "Increased NTRK1 IHC (higher than the level of normal mucosa) was found in 73 of 93 cases (78.50%), whereas increased p75NTR IHC (at least 33% of the cells in tumor cell nests positive) was found in 20 of 93 cases (21.50%)." (PMID 29904026, 2018). "Although the tumor histology varied widely in this study, the median progression-free survival for patients harboring rearrangements in NTRK1/2/3, ROS1, and ALK is 19.0 months." (PMID 29617282, 2018). "Most importantly the co-expression of NTRK1 and p75NTR can be observed at tumor cell nest or at whole culture level, but in fact, it means separated NTRK1- and p75NTR-positive cells." (PMID 29904026, 2018). "NTRK1 clearly co-localized with cytokeratin in established cancer cell nests as well as in small cytokeratin-positive groups of disseminating tumor cells (Figure A1)." (PMID 29904026, 2018). "Across all tumour types analysed, NTRK1–3 fusions were observed at low frequency in 9 of the 20 cancer types analysed, providing a therapeutic opportunity for the use of pan-NTRK inhibitors in multiple patient populations." (PMID 25204415, 2014). "The present study extends our knowledge of NTRK1-regulated processes to the field of tumor-stroma interactions." (PMID 25361003, 2014). "Cell-based and xenograft assays using NTRK1 inhibitors in NTRK1 transformed cells led to inhibition of cellular proliferation and tumor shrinkage, respectively, indicated NTRK1 rearrangement are indeed a driver mutation in NSCLC." (PMID 24744988, 2014).
tumor (continued). "A novel in-frame gene fusion (TMEM79::NTRK1) was identified in a single tumor sample (0.5%)." (PMID 41977128, 2026). "Alternative NTRK1/TrkA splicing, resulting in expression of the TrkAIII splice variant (GeneBank OP866787), represents a potential oncogenic alternative to Trk-fused genes in different tumor types." (PMID 39941839, 2025). "Further, ThyroSPEC study of the primary tumor demonstrated a TPR::NTRK1 fusion-positive tumor (without TERT promoter mutations)." (PMID 38642578, 2024). "The use of alternative molecular testing methods such as direct sequencing or in situ hybridization is not recommended because of the diversity of NTRK fusions observed in various central nervous system (CNS) tumours, with NTRK1/2/3 interacting with multiple fusion partners." (PMID 39014476, 2024). "IHC testing was positive for anaplastic lymphoma kinase (ALK) protein (2+ staining intensity, 30% of tumor sample) and neurotrophic tyrosine receptor kinase TRK/NTRK (80%), suggesting that either ALK or TRK/NTRK1/2/3 could be a targetable driver in the tumor." (PMID 36619485, 2023). "In multiple tumor types, a constitutive activation of NTRK1 was observed." (PMID 37446908, 2023). "This gene family encodes tropomyosin receptor kinases (TRKA, TRKB, and TRKC), and fused NTRK genes (NTRK1, NTRK2, NTRK3) translate a TRK fusion protein that activates tyrosine kinases and constitutively stimulates the growth of tumor cells." (PMID 37895255, 2023). "Here, we investigated whether growth factors produced in the tumor microenvironment can induce resistance to entrectinib in tumor cells with NTRK1 or ROS1 rearrangements." (PMID 36416133, 2023). "NTRK1, therefore, produces a wider range of TrkA protein isoforms than previously considered, with tumour-suppressing and oncogenic potential, and TrkAIII represents the pathological equivalent of a previously reported engineered oncogenic TrkA D4-deletion mutant." (PMID 36672171, 2023). "HPV-positive tumors showed unique deletions of tumor suppressors such as NTRK1 and JAK1." (PMID 37461056, 2023). "For instance, although the morphologic spectrum of neurotrophic tyrosine receptor kinase (NTRK) fusion tumors was heterogenous, and included an undesignated tumor lineage, NTRK1-3 fusions in solid tumors were revealed as tumor-agnostic marker of response to treatment with a selective inhibitor." (PMID 36033527, 2022). "NTRK1 fusion was detected in three tumor samples, and two samples harbored NTRK3 fusions." (PMID 35681640, 2022). "Subsequent identification of ALK rearrangements and several cancer‐driver events, including ROS1, NRG1, NTRK1/RET fusion, BRAF (V600E) mutation, or MET amplification/Exon14 skipping, strengthened the concept of oncogene addiction and tumor heterogeneity as a pillar of modern cancer therapeutics." (PMID 35838331, 2022). "However, the tumor-suppressive behavior of NTRK1 in PCa is controversial as many studies have delineated the pro-tumorigenic role of NTRK1 in PCa." (PMID 35627227, 2022). "Tumor samples from 31 patients were tested for NTRK1, NTRK2, and NTRK3 fusion by FISH analysis." (PMID 35681640, 2022). "NTRK1 fusions were detected in three tumor samples, and two samples harbored NTRK3 fusions." (PMID 35681640, 2022). "Indeed, papillary thyroid carcinoma (PTC) was one of the first tumour types in which NTRK1 fusions were identified." (PMID 35333737, 2022). "Studies have shown that increased expressions of regular NTRK1 isoforms (TrkAI/II) in normoxia played an antioncogenic role, while under hypoxic conditions, the upregulation of TrkAIII plays an oncogenic role in tumor progression and metastasis PI3K/Akt signaling." (PMID 36483920, 2022). "Interestingly, the IRF2BP2::NTRK1 containing tumour was the only one located to the left colon (sigma) amongst our NTRK1 fusion–positive cases." (PMID 35237889, 2022).
tumor (continued). "The tumor-specific DNA markers including point mutations in EGFR or BRAF genes, rearrangements involving ALK or ROS1 genes and fusions of NTRK1/2/3 genes along with tumor mutation burden (TMB) and PDL-1 RNA expression serve as guides in proper therapy selection." (PMID 35837614, 2022). "This suggests that CHRNB4 may promote tumor development by directly affecting tumor cells, and NTRK1 may change the tumor microenvironment by affecting mast cells." (PMID 34912722, 2021). "By contrast, more benign disease courses, frequently associated with TrkA/NTRK1 expression, are characterized by near-triploid tumor genomes suggesting defects in mitotic control rather than genomic instability." (PMID 34885133, 2021). "NTRK gene fusions involving NTRK1, NTRK2 and NTRK3 (encoding receptor proteins TRKA, TRKB and TRKC, respectively) are responsible for many neoplasms in both adults and children, including rare cancers such as secretory breast carcinoma and infantile fibrosarcoma." (PMID 33921237, 2021). "Moreover, we confirmed the mutation in ARID1A gene (p.R1276∗), ERBB3 (p.S128R), KEAP1 (p.R135H), PALB2 (p.P807S), and NTRK1 (p.Q736X), previously reported by F1CDx, both in the tumor and in the ccfDNAs." (PMID 34178989, 2021). "Furthermore, there were two genes (FBXW7, RET) mutated exclusively in tumours and eight (BLM, GJB2, NOTCH2, NOTCH3, NTRK1, POLE, SOS1, TSC2) solely in metastases." (PMID 34572946, 2021). "Then, we selected 16 GC patients overexpressing NTRK1–3, defined as a ≥2.0-fold change; the incidence was 47%, which was much higher than the rate reported in previous studies on 17–33 different tumor types (2.2–14.2%)." (PMID 35008821, 2021). "Furthermore, NTRK1 fusion-positive carcinomas differed from carcinomas harboring the NTRK3 fusion gene by higher frequencies of tumor multifocality, distant metastases and carcinoma invasiveness." (PMID 33923728, 2021). "For example, tumor-agnostic biomarkers such as micro-satellite instability, oncogenes like NTRK1, NTRK2, and NTRK3, and the recently United States Food and Drug Administration (FDA)-approved tumor mutation burden, are used for tumor-agnostic patient stratification and therapeutic decisions." (PMID 33396205, 2020). "In HER2-enriched tumours, only 3% of cases presented with NTRK1 alterations." (PMID 32957504, 2020). "TrkA (NTRK1) gene overexpression has also been shown to occur preferentially in invasive tumours." (PMID 32957504, 2020). "However, an NTRK1 fusion tumor showed strong and diffuse cytoplasmic staining under the similar conditions." (PMID 33127954, 2020). "Clinical information for analysis included DE-mRNA signature, age, PFI status, mutational status of BRAF V600E, RAS, RET, NTRK1, and TERT, sex, histological subtype, T stage, N stage, M stage, AJCC stage, residual tumor status, extrathyroidal extension, multifocality, and anatomic site." (PMID 33553144, 2020). "Additionally, analysis of tumor-infiltrating T cell populations revealed that Ntrk1 can promote CD8+ T cell exhaustion." (PMID 30986992, 2019). "Specifically, Ntrk1 expression can promote CD8+ T cell exhaustion within the tumor microenvironment, suggesting that its expression may contribute to CD8+ T cell dysfunction and thus diminish response to PD-1 inhibition." (PMID 30986992, 2019). "However, when challenged with a PD-1 blocking antibody and therefore under immune system pressure, Ntrk1 then becomes essential for tumor cell survival." (PMID 30986992, 2019). "Aside from the alterations seen in primary SC tumor tissue, the relapsed SC acquired a novel PHF20-NTRK1 fusion where PHF20 intron 2 fused to the intron 4 of NTRK1 at a high variant allele frequency (VAF), resulting in a PHF20-exon 2: NTRK1-exon 5 fusion mRNA with potential in-frame translation." (PMID 31208361, 2019).
tumor (continued). "To determine how Ntrk1 may be modulating tumor growth and the immune microenvironment, we examined Jak/Stat signaling as a function of Ntrk1 expression; this is a known pathway utilized by tumors to promote immunosuppression." (PMID 30986992, 2019). "Additionally, we confirmed by genomic PCR and FISH analysis the presence of the Bcan-Ntrk1 gene fusion on cells isolated from the tumor-bearing mice, propagated in vitro as tumorspheres." (PMID 29654229, 2018). "NGF might improve cell survival after a cell cycle arrest in tumor cell nests (or cell culture), which contain sufficiently high number of cells with NTRK1." (PMID 29904026, 2018). "However, consistent with prior published reports of tumor growth inhibition in NTRK1 rearranged patients treated with entrectinib, our data showed that this drug has a significant therapeutic potential against newly identified NTRK1 gene rearrangements." (PMID 28903424, 2017). "More recently, NTRK1 rearrangements have been further identified in other tumor types, including Spitzoid melanoma (16.4%, 23/140), intrahepatic cholangiocarcinoma (3.6%, 1/28), glioblastoma (1.1%, 2/185), pediatric high grade glioma (7.1%, 8/112) and sarcoma (1%, 1/103)." (PMID 26472021, 2015). "Furthermore, expression of NTRK1, leading to reduced proliferation and angiogenesis, constitutes a selective disadvantage for tumor cells." (PMID 25361003, 2014). "Neither germ-line nor somatic gain-of-function mutations of the NTRK1 gene have been observed in any human neoplasia, except for one case of a de novo AML." (PMID 20003389, 2009). "Furthermore, NTRK1, encoding the Neurotrophic Receptor Tyrosine Kinase 1, was found to harbor a missense variant (p.T741P) of unknown significance (VUS) in the tyrosine kinase (TK) domain in tumor and matched organoids." (PMID 35789568, 2022). "Indeed, there were a few differences between patient tumor, PDOX, and cell line, such as NTRK1 mutation detected in the autopsy sample of SJ-DIPGX37, but not the associated PDOX or cell line, or MYCN amplification present in SJ-DMGX40 PDOX, but not in the matched patient tumor." (PMID 34215733, 2021). "Additionally, we reported that the size of the tumor, positivity for NTRK3 or NTRK1 fusion, the presence of metastases and late mutation events may provide prognostic information for patient outcomes." (PMID 33923728, 2021). "In addition, one NTRK1 fusion was detected by FISH in a tumor overexpressing panNTRK (T24)." (PMID 33435234, 2021). "Importantly, Ntrk1 is a top hit across both time points of tumor collection and sequencing, suggesting the validity of this gene as a positive hit from the screen that is more likely to play a role in PD-1 treatment resistance in the face of long-term treatments." (PMID 30986992, 2019). "NTRK1, NTRK2, and NTRK3 gene fusions are rare oncogenic driver alterations found in diverse tumor types of adults and children." (PMID 40385986, 2025). "Also, OncoPrism-HNSCC leverages the same FFPE patient tumor RNA used for ICI response prediction to identify rare cases where oncogenic rearrangements in NTRK1/2/3 or ALK genes may occur, and which may indicate the use of potentially highly effective targeted therapies." (PMID 39773366, 2025). "Gene fusions primarily comprising RET, NTRK1 or NTRK3 and more rarely ALK or MET genes are among the most commonly described as tumor drivers in pediatric PTC." (PMID 40338900, 2025). "The NTRK2 gene was not examined by FISH, but NTRK2 gene fusions are reported to be even much rarer than NTRK1 and NTRK3 gene rearrangements in other neoplastic diseases." (PMID 40235191, 2025). "NTRK fusions involve the fusion of NTRK1, NTRK2, or NTRK3 with various partner genes, leading to constitutive activation of the TRK signaling pathway, which promotes tumor growth, survival, and metastasis." (PMID 40363930, 2025).